FTO (FTO alpha-ketoglutarate dependent dioxygenase)
Diseases named in the same sentence as FTO in open-access papers (continued):
Sharing a sentence is not in itself a finding about the gene and the disease.
Obesity (continued). "Fat mass and obesity associated (FTO) gene was the first obesity associated locus implicated by GWAS." (PMID 23091647, 2012). "Currently, energy intake is the only obesity-associated trait significantly and repeatedly associated with FTO variants in humans." (PMID 22675562, 2012). "In the Alzheimer's Disease Neuroimaging Initiative (ADNI), the FTO polymorphism most commonly associated with obesity and in Caucasians (rs9939609 (Intron 1)) was associated with reductions in frontal and occipital lobe volumes." (PMID 23251365, 2012). "The discovery of these loci has initiated a series of experiments to explore the pathophysiological mechanisms that underlie obesity development, in particular to the fat mass and obesity-associated (FTO) gene." (PMID 22474595, 2012). "In a recent meta-analysis, physical activity level was shown to modify the relationship between the FTO risk variant and body weight and risk of obesity." (PMID 23284729, 2012). "Single nucleotide polymorphisms (SNPs) in the fat mass and obesity–associated (FTO) gene, known to influence the risk of obesity, have also been associated with BMD in Chinese populations, based on a recent study reporting lower BMD in mice lacking Fto." (PMID 23300848, 2012). "Subsequently, this significant association of FTO with obesity has been further replicated in other independent populations." (PMID 23049848, 2012). "In particular, we observe that the association between FTO gene and BMI strongly influences the age of onset of obesity, with the carriers of the “at risk” alleles showing a significantly higher prevalence in younger age." (PMID 22454631, 2012). "The relationship between obesity and the TE type by the risk alleles of FTO and MC4R was consistent with the findings of a previous report, which indicated that TE subjects tend to have higher fat masses." (PMID 19822564, 2011). "We observed a strong association of obesity to the FTO gene, with the most significantly associated marker being rs3751812 (P = 2.01×10−8, odds ratio = 1.64)." (PMID 21552555, 2011). "Three studies suggest that a high fat diet can amplify the effect of the FTO genotype on obesity risk." (PMID 22043165, 2011). "These functional results provide new ideas for deducing the mechanisms affected by obesity related FTO-risk alleles." (PMID 22087873, 2011). "We therefore sought out to find other links between obesity, DM and breast cancer, which lead us to evaluate the role of FTO in breast cancer risk." (PMID 21489227, 2011). "Genome-wide association studies have provided evidence for a relationship between prevalent variants in the fat mass and obesity associated (FTO) gene and obesity." (PMID 21637715, 2011). "Recent genome-wide association (GWA) studies allowed identifying several genetic factors associated with childhood and adult obesity, such as variants of the FTO and MC4R genes." (PMID 21526213, 2011). "The odds of obesity for the FTO risk allele were 27% smaller (odds ratio [OR] = 1.22 versus 1.30, respectively) and the odds of overweight were 26% smaller (OR = 1.14 versus 1.19, respectively) in physically active individuals than in inactive individuals." (PMID 22069379, 2011). "Experimental animal studies provide direct functional evidence that FTO is a causal gene underlying obesity." (PMID 22125610, 2011). "Association of the minor (A−) allele of the rs9939609 SNP or a proxy (r2>0.8) in the FTO gene with BMI, waist circumference, body fat percentage, risk of obesity, and risk of overweight in a random effects meta-analysis of up to 218,166 adults." (PMID 22069379, 2011). "Research on FTO, where the minor allele of rs9939609 is a well established risk-factor for adult obesity, illustrates the importance of a developmental perspective." (PMID 22174699, 2011). "Previous studies have demonstrated a common variant of the obesity and fat mass-related FTO gene, rs9939609, to be associated with obesity, type 2 diabetes, and elevated blood pressure." (PMID 22132335, 2011).
Obesity (continued). "BMI has been the most widely used measurement in the majority of studies between obesity and genetic variants in FTO, most likely due to its simple acquisition and calculation." (PMID 21637715, 2011). "Each additional minor allele of the rs9939609 single nucleotide polymorphism (SNP) in FTO was found to be associated with a 20%–30% increase in the risk of obesity and a 1–1.5 kg increase in body weight." (PMID 22069379, 2011). "The association of the FTO rs9939609 variant with BMI and with the odds of obesity was reduced by approximately 30% in physically active compared to inactive adults." (PMID 22069379, 2011). "The fat mass and obesity associated (FTO) gene represents the first gene identified that contributes to common forms of human obesity." (PMID 22043166, 2011). "Nineteen loci have been identified and five of them only are associated with BMI / obesity (FTO, MC4R,NRXN3, TFAP2B, MSRA)." (PMID 22043164, 2011). "The association of the FTO region to obesity explains ∼1% of BMI heritability, such that adults homozygous for the risk allele, have a 2–3 kg higher weight compared to non-risk allele homozygous." (PMID 21466928, 2011). "It was already known that certain variants of the “fat mass and obesity associated” (FTO) gene predispose to weight gain, but this article shows that this effect is weaker among physically active persons." (PMID 22069377, 2011). "Recently, several independent large-scale genome-wide association studies (GWAS) consistently identified a gene FTO (fat mass and obesity associated) to be associated with obesity-related traits and obesity risk." (PMID 22125610, 2011). "Although important gaps exist in our understanding of the molecular pathways leading to increased weight and obesity, our data provide novel evidence that the FTO rs9939609 AA genotype is associated with endometrial cancer risk among non-Hispanic white women." (PMID 21347432, 2011). "In this way, single nucleotide polymorphisms (SNPs) in the first intron of the fat mass and obesity-associated (FTO) gene were found to be associated with obesity in numerous human populations." (PMID 22140494, 2011). "In 2007, four different approaches led to the identification of variation in the intron 1 of Fat mass and obesity associated (FTO) gene as the major contributor to polygenic obesity in populations of European ancestry." (PMID 22043164, 2011). "FTO is a novel gene which has been identified through genome wide association studies (GWAS) to be related to obesity." (PMID 21489227, 2011). "The rs9939609 single-nucleotide polymorphism (SNP) in the fat mass and obesity (FTO) gene has previously been associated with higher BMI levels in children and young adults." (PMID 21637715, 2011). "Follow-up studies have confirmed the association between FTO and obesity-related phenotypes not only in populations of European ancestry but also in African, Asian, South Asian, South American and Pima Indian populations." (PMID 22043165, 2011). "Consistent with the meta-analysis of BMI, PA attenuated the effect of the FTO risk allele on the odds of obesity (pinteraction = 0.001) and on the odds of overweight (pinteraction = 0.02)." (PMID 22069379, 2011). "Ruth Loos and colleagues report findings from a meta-analysis of multiple studies examining the extent to which physical activity attenuates effects of a specific gene variant, FTO, on obesity in adults and children." (PMID 22069379, 2011). "The strongest impact on BMI was with Fat mass and obesity associated (FTO), a gene already identified as an obesity risk." (PMID 21980424, 2011). "A genome-wide search for type 2 diabetes-susceptibility genes identified a common variant in the Fat mass and Obesity associated (FTO) gene on chromosome 16." (PMID 21980407, 2011). "Given the association between obesity and breast cancer we elected to perform a case control study to evaluate the role of SNPs in intron 1 of FTO in predicting breast cancer risk." (PMID 21489227, 2011).
Obesity (continued). "Although overweight is a major risk factor of pregnancy-induced hypertension and PE, we were unable to demonstrate an association between the obesity-predisposing rs9939609 of FTO and PE in this study." (PMID 22132335, 2011). "In contrast, a number of earlier positive studies for the association between the FTO gene and obesity have been done in children and adolescents." (PMID 21637715, 2011). "This is analogous to the inter-related pathways underlying obesity and type 2 diabetes, where the FTO (Fat mass and obesity associated) gene has been implicated in both diseases." (PMID 21304900, 2011). "The FTO gene has been associated with food intake and reduced satiety response, and the genetic effect on obesity is attenuated by physical activity." (PMID 19822564, 2011). "Consistent with previous studies, we replicated the association of MC4R with BMI in a Korean population for the first time and we also confirmed the association of the FTO LD block with obesity-related phenotypes in Koreans." (PMID 19822564, 2011). "The FTO gene has become the hotspot for researchers since it was reported as a novel obesity-susceptibility gene by a number of GWAS and follow-up replication studies." (PMID 22125610, 2011). "The Fat mass and obesity gene (FTO) has been identified through genome wide association studies as an important genetic factor contributing to a higher body mass index (BMI)." (PMID 22087873, 2011). "Single-nucleotide polymorphisms (SNPs) of the fat mass and obesity associated (FTO) gene have been linked to increased risk of obesity." (PMID 21980407, 2011). "In adults, each additional risk allele of the FTO rs9939609 variant increased the odds of obesity and overweight by 23% (p = 7×10−59) and 15% (p = 6×10−66), respectively." (PMID 22069379, 2011). "Thirteen independent studies reported an interaction between the FTO obesity risk genotype and physical activity on BMI variation or obesity risk including adults as well as adolescents." (PMID 22043165, 2011). "Single-nucleotide polymorphisms (SNPs) in the FTO locus were associated with early-onset and severe obesity across different ethnic cohorts." (PMID 21980407, 2011). "In summary, we have established that PA attenuates the association of the FTO gene with adult BMI and obesity by approximately 30%." (PMID 22069379, 2011). "The first gene unequivocally associated to common, non-syndromic obesity, FTO (fat mass and obesity associated), was initially identified as a result of a GWA of T2D." (PMID 21466928, 2011). "To examine the relation between the obesity-associated FTO rs9939609 and MC4R rs17782313 and endometrial cancer risk, we utilized pooled data within the Epidemiology of Endometrial Cancer Consortium (E2C2)." (PMID 21347432, 2011). "The association of the FTO risk allele with the odds of obesity is attenuated by 27% in physically active adults, highlighting the importance of PA in particular in those genetically predisposed to obesity." (PMID 22069379, 2011). "We obtained strong support for FTO as well as suggestive confirmation of several previously identified BMI-associated genes in obesity." (PMID 21552555, 2011). "Given the evidence that obesity and osteoporosis share some common genetic determinations, we first performed an association study examining the SNPs in FTO for association with BMD." (PMID 22125610, 2011). "A few smaller GWAs focused on other forms of obesity (early onset, extreme obesity and/or morbid adult obesity) and replicated FTO, MC4R and TMEM18 BMI-associations." (PMID 21466928, 2011). "Single-nucleotide polymorphisms in the first intron of the ubiquitously expressed FTO gene are associated with obesity." (PMID 22140494, 2011). "Experimental evidence suggests that obesity associated SNPs in intron 1 of the FTO gene are associated with altered gene expression." (PMID 21347432, 2011).
Obesity (continued). "Genome-wide association studies in several ethnic populations have shown a common variant of the highly polymorphic obesity and fat mass-related FTO gene, rs9939609 (T/A), located on chromosome 16q2, to be associated with obesity and T2DM." (PMID 22132335, 2011). "For obesity variants, we selected 7 FTO SNPs (rs1421085, rs1121980, rs8057044, rs8050136, rs9939609, rs9941349 and rs9930506) and 2 MC4R SNPs (rs17782313 and rs12970134)." (PMID 21573225, 2011). "The obesity predisposing FTO variant was associated with increased total and fat dietary intake in children as well as in adults." (PMID 22043165, 2011). "Recently, analysis of GWAS-derived obesity gene variants provided evidence of positive natural selection at the FTO, NEGR1, SH2B1 and FAIM2 loci." (PMID 22043165, 2011). "Previously, various genes including the fat mass and obesity associated (FTO) and the nicotinamide phosphoribosyltransferase (NAMPT) gene have been suggested to potentially contribute to the development of obesity and related metabolic traits." (PMID 21687707, 2011). "The most recent GWAS has confirmed that the FTO gene, in addition to two other obesity susceptibility genes (MC4R and NPC1, reviewed below) are associated with childhood and adult obesity within a European population." (PMID 22043166, 2011). "A potential role for FTO in the development of obesity was proposed by studies in mice showing that Fto deficiency resulted in reduced body weight and white adipose tissue mass." (PMID 21687707, 2011). "Hitherto, the A-allele of the FTO rs9939609 is the genetic variant most strongly associated with common obesity." (PMID 21246032, 2011). "The fat mass and obesity associated (FTO) gene has an important genetic effect on body mass index (BMI) and risk of obesity, and obesity contributes to the progression of renal diseases, including diabetic nephropathy." (PMID 20467478, 2010). "Several other studies also found positive association between FTO rs9939609 and the risk of obesity (OR = 1.43, OR = 1.38 and OR = 1.39 respectively) in the East Asian adults." (PMID 20858286, 2010). "A second relevant example is rs9939609, a SNP located in the fat mass and obesity associated (FTO) gene." (PMID 21286314, 2010). "Given the association of FTO with human obesity, we wished to determine if the expression of FTO is influenced by food intake." (PMID 21103374, 2010). "In conclusion, we show that common variations nearby the TMEM18 gene are associated not only to adult obesity but also obesity in severely obese children in a similar magnitude as FTO, the first gene associated with the common form of obesity." (PMID 20380707, 2010). "It would require more power to detect the associations between FTO genotype and other obesity-related metabolic traits." (PMID 20858286, 2010). "For instance, common variants in the fat mass and obesity associated gene (FTO) predispose to an elevated body mass index (BMI) with an increase of 0.36 kg/m2 BMI units per risk allele." (PMID 20092643, 2010). "For white participants, the FTO rs9939609 A allele was associated with an increased risk of diabetes (odds ratio (OR) = 1.19, p<0.001) and obesity (OR = 1.22, p<0.001) under an additive genetic model that was similar for all of the SNPs analyzed." (PMID 20502638, 2010). "Absolute methylation levels were quantified across LD blocks, and we identified increased DNA methylation on the FTO obesity susceptibility haplotype, tagged by the rs8050136 risk allele A (p = 9.40×10−4, permutation p = 1.0×10−3)." (PMID 21124985, 2010). "A single nucleotide polymorphism (SNP), known to be associated with obesity (FTO rs9939609), has been robustly associated with increased body mass index (BMI) and obesity in multiple study populations." (PMID 20976066, 2010). "The purpose of this study is to replicate the associations of FTO rs9939609 with obesity and obesity-related metabolic traits in Chinese children." (PMID 20858286, 2010).
Obesity (continued). "Two SNPs in the FTO gene, which has a well-established association with obesity, were genotyped in our study (rs8050136 and rs3751812), and showed only weak association with WHR (p = 4.6×10−3 and 4.4×10−3)." (PMID 20694148, 2010). "To compare the effect of FTO obesity risk alleles on BMI in patients with PCOS to unselected females of the same age range we genotyped 1,971 females from the population-based KORA-S4 study (Kooperative Gesundheitsforschung im Raum Augsburg, Survey 4)." (PMID 20092643, 2010). "Multiple studies have provided compelling evidence that the FTO gene variants are associated with obesity measures." (PMID 20442772, 2010). "We aimed to test the association of FTO genetic variants with obesity and obesity-related metabolic traits among children living in Beijing, China." (PMID 20858286, 2010). "Genome-wide association studies found common variants in the fat mass and obesity-associated (FTO) gene associated with adiposity in Caucasians and Asians but the association was not confirmed in African populations." (PMID 20377915, 2010). "The relationship between diabetes, four previously identified FTO polymorphisms, and obesity was evaluated in the biracial population-based ARIC cohort study in an initial effort to fine map the association by comparing results between two racial groups." (PMID 20502638, 2010). "In 2007, single nucleotide polymorphisms (SNPs) within the fat mass and obesity-associated gene (FTO) became the first to be associated reproducibly with human body mass." (PMID 20381893, 2010). "In summary, we replicated that the genetic variation in the FTO gene associates with obesity in the Chinese children." (PMID 20858286, 2010). "A common genetic polymorphism, rs9939609, in the FTO gene is found to associate with BMI and predisposes to childhood and adult obesity." (PMID 20467478, 2010). "The association between FTO and obesity has been shown to indirectly modulate risk of type 2 diabetes in Europeans, but it has been difficult to demonstrate an association between FTO (rs8050136) and obesity or BMI in Asians." (PMID 20161779, 2010). "In 2007, several groups reported that a cluster of SNPs (single nucleotide polymorphism) in the first intron of FTO was highly associated with obesity-related traits and higher obesity risk." (PMID 21103374, 2010). "The obesity-risk-allele score based on genotypes at eight SNPs associated with childhood BMI (in/near to: FTO, MC4R, TMEM18, GNPDA2, NEGR, KCTD15, BDNF, and ETV5) ranged from 2 to 15 alleles." (PMID 20520848, 2010). "A meta-analysis combining all studies in East Asian populations showed that the FTO rs9939609 polymorphism is associated with obesity." (PMID 20598163, 2010). "The SNPs in FTO that are associated with obesity in humans reside in the intronic region and their effect on the function of FTO remains elusive." (PMID 21103374, 2010). "In conclusion, we have identified variant-CpG restricted Haplotype-Specific Methylation within the FTO obesity susceptibility locus." (PMID 21124985, 2010). "While the effect sizes of these variants contributing to the risk of obesity are modest, the fat mass obesity-associated (FTO) gene region has been replicated in several studies and in multiple populations." (PMID 20442772, 2010). "The FTO rs9939609 variant is strongly associated with BMI and the risk of obesity in a population of children and adolescents in Beijing, China." (PMID 20598163, 2010). "This strengthens previous observations that this region is as strongly associated with obesity as FTO." (PMID 20380707, 2010). "Our study was therefore sufficiently powered to validate the association between FTO markers and obesity related anthropometric measures." (PMID 20442772, 2010). "Only one of the genetic variants (rs1421085) was associated with both diabetes and obesity in African-Americans, while all of the FTO polymorphisms were determinants of disease risk in whites as shown in other studies." (PMID 20502638, 2010).